PCDHGB6 (protocadherin gamma subfamily B, 6)
Description:
Potential calcium-dependent cell-adhesion protein. May be involved in the establishment and maintenance of specific neuronal connections in the brain.
Synonyms: PCDH-gamma-B6
Tractability: Antibody: UniProt places it where antibodies can reach, with medium confidence; UniProt predicts a signal peptide or a membrane-spanning region; its Gene Ontology location is reachable by antibodies, with medium confidence. PROTAC: its protein half-life has been measured.
Gene: Protein-coding gene on chromosome 5 (141,408,021 to 141,512,975, forward strand). Ensembl gene ENSG00000253305.
Subcellular location: Cell membrane
Subcellular location (Human Protein Atlas): Plasma membrane; Vesicles; Cytosol; Nucleoplasm
Gene Ontology:
Molecular function: cell adhesion molecule binding; calcium ion binding
Biological process: cell adhesion; homophilic cell-cell adhesion
Cellular component: plasma membrane; membrane
Genetic constraint (gnomAD): Loss-of-function variants: 51 observed, 63.04 expected, observed/expected ratio (o/e) 0.81, 90% interval 0.64 to 1.02. The upper end of that interval is the gene's LOEUF score, 1.02, which puts it in group 4 of 6, group 1 being the genes least tolerant of losing a copy. Missense variants: 1,148 observed, 1,280.5 expected, observed/expected ratio (o/e) 0.9, 90% interval 0.85 to 0.94. Synonymous variants: 466 observed, 529.38 expected, observed/expected ratio (o/e) 0.88, 90% interval 0.81 to 0.95.
Homologues: Orthologues: mouse Pcdhgb6 (83% identical). Paralogues in human: PCDHGB7 (78% identical), PCDHGB5 (73% identical), PCDHGB1 (71% identical), PCDHGB2 (70% identical), PCDHGB4 (70% identical), PCDHGB3 (67% identical), PCDHGA6 (52% identical), PCDHGA12 (52% identical), PCDHGA5 (52% identical), PCDHGA11 (51% identical), PCDHGA7 (51% identical), PCDHGA3 (51% identical), and 49 more.
Diseases named in the same sentence as PCDHGB6 in open-access papers:
PCDHGB6 is named in the same sentence as 4 diseases in open-access papers, as found by Europe PMC text mining. Sharing a sentence is not in itself a finding about the gene and the disease. The quoted sentences say what the papers report.
non-small cell lung carcinoma (2 papers, 2016 to 2021). A group of at least three distinct histological types of lung cancer, including non-small cell squamous cell carcinoma, adenocarcinoma, and large cell carcinoma. "In addition, Esteller and the associates used methylation array to establish methylation profiles of stage I Caucasian non-small cell lung cancer and identified that methylation of two or more genes in HIST1H4F, PCDHGB6, NPBWR1, ALX1, and HOXA9 correlated with an increased risk of cancer recurrence." (PMID 27484806, 2016).
breast carcinoma (1 paper, 2009). "We were also able to identify several genes, such as CDKN2A, PCDHGB6, and WT1 well known to be methylated and transcriptionally silent in breast cancer." (PMID 19250546, 2009).
PCDHGB6 also shares sentences with these, for which no sentence is quoted: cancer (1 paper); tumor (1).